CCND1 (cyclin D1)
Diseases named in the same sentence as CCND1 in open-access papers (continued):
Sharing a sentence is not in itself a finding about the gene and the disease.
bladder cancer (153 papers, 1999 to 2026). "CCND1 is a highly conserved cyclin, and its amplification is a risk factor for bladder cancer metastasis." (PMID 41287122, 2025). "After hnRNP-F knockdown, TPX2 levels were found to decline even further, causing cyclin D1 protein expression to decrease and p21 protein expression to increase, resulting in cell cycle arrest and the reduced proliferation of bladder cancer cells." (PMID 36304254, 2022). "The CCND1 gene encoding CCND1 is activated in B-cell lymphomas and overexpressed in many other human cancers (esophageal, lung, breast, bladder carcinomas, etc.)where it acts as a proto-oncogene." (PMID 34445095, 2021). "We also found regorafenib significantly reduces tumor growth, NF‐κB activation, and protein levels of tumor progression‐associated proteins (MMP‐9, XIAP, VEGF, and Cyclin‐D1) in bladder cancer in vitro and in vivo." (PMID 30801954, 2019). "Mechanistically, hnRNPK regulated various functions in bladder cancer by directly mediating cyclin D1, G0/G1 switch 2 (G0S2), XIAP‐associated factor 1, and ERCC excision repair 4, endonuclease catalytic subunit (ERCC4) transcription." (PMID 27862976, 2017). "This meta-analysis aimed to examine the association between increased cyclin D1 expression and the prognosis of bladder cancer patients." (PMID 24602161, 2014). "Increased cyclin D1 expression level detected by immunohistochemistry is associated with good progression-free survival for bladder cancer." (PMID 24602161, 2014). "In summary, despite the limitations, results of our meta-analysis suggest that increased cyclin D1 expression is significantly associated with good PFS in bladder cancer." (PMID 24602161, 2014). "Currently, there are several genetic polymorphisms which have been identified as risk factors of bladder cancer, such as cyclin D1 (CCND1) G870A polymorphism and NQO1 C609T polymorphism." (PMID 24390660, 2014). "Amplification of cyclin D1, a key cell cycle regulatory protein, appears to be an important event in bladder cancer and is often associated with cell proliferation and poor prognosis in human tumors." (PMID 19878607, 2009). "In addition to FGFR3, alterations in a number of other genes including MYC and CCND1 (encoding cyclin D1), are found in bladder cancers and thought to contribute to oncogenesis." (PMID 29423038, 2018). "Moreover, the polymorphism within the cyclin D1 gene was associated with risk and clinicopathologic characteristics of urinary bladder cancer." (PMID 24351837, 2013). "Notably, this study found that the expression levels of AKT1, GSK3B, CASP3, TNF, and CCND1 were associated with immune cell infiltration in bladder cancer, suggesting that these targets could be used as potential predictors of bladder cancer immunotherapy." (PMID 41287122, 2025). "Therefore we assume that long-term administration of temsirolimus to bladder cancer cells may result in a feedback mechanism characterized by re-activation of Raptor, associated with cyclin A and cyclin D1 elevation and loss of p27." (PMID 29299126, 2017). "Our previous study has shown that c-myc mRNA impairment is crucial for p63α inhibition of Cyclin D1 gene transcription and bladder cancer cell tumorigenicity." (PMID 40224178, 2025). "RAC-alpha serine/threonine-protein kinase 1 (AKT1), glycogen synthase kinase 3 beta (GSK3B), caspase-3 (CASP3), tumor necrosis factor (TNF) and cyclin D1 (CCND1) were identified as the main hub targets of COP in bladder cancer treatment." (PMID 41287122, 2025).
bladder cancer (continued). "The results revealed high expression of Cyclin D1 in bladder cancer cells, and silencing Cyclin D1 significantly slowed cell proliferation, indicating that Cyclin D1 is an effective potential target for treating bladder cancer." (PMID 40083696, 2025). "The observed regulation of the SMAD4/C-MYC/Cyclin D1 axis by miR-146b underscores its potential as a key modulator in bladder cancer progression." (PMID 40224178, 2025). "Our previous study has shown that C-MYC is a promotive transcription factor of Cyclin D1 by directly binding to its promoter region, which plays a critical role in human bladder cancer cell tumorigenicity." (PMID 40224178, 2025). "Our group found that Cyclin D1 downregulation was responsible for the isorhapontigenin-induced anticancer effect on human bladder cancer cells." (PMID 40224178, 2025). "In conclusion, the results indicated that Cyclin D1 is a critical downstream effector for miR-146b mediating bladder cancer cell growth." (PMID 40224178, 2025). "Direct impact of TRIM29 is noticeable in bladder cancer, where Bcl family protein and cyclin D1/E levels are enhanced by TRIM29 through the PKC-NF-κB signaling pathway thus resulting in reduced apoptosis with an increase in proliferation signal." (PMID 40420099, 2025). "Our findings provide novel insights into the role of miR-146b in regulating the SMAD4/C-MYC/Cyclin D1 axis in bladder cancer, aligning with previous studies demonstrating miR-146b’s oncogenic potential in various malignancies." (PMID 40224178, 2025). "In this study, we propose that miR-146b-induced repression of SMAD4 leads to enhanced C-MYC expression and subsequent upregulation of Cyclin D1, facilitating the rapid growth and metastasis of bladder cancer cells." (PMID 40224178, 2025). "Cyclin D1 has been reported to be responsible for miR-576-3p overexpression inhibiting human bladder cancer proliferation by directly binding with its 3′-UTR." (PMID 40224178, 2025). "Based on our data, we conclude that MIR4435-2HG exerts versatile functions in bladder cancer by transcriptionally regulating the expression of multiple cell-cycle regulators such as CCND1 and BRCA2." (PMID 37355516, 2023). "For example, the STAT3 pathway regulates the proliferation and migration of drug-resistant bladder cancer cells by regulating Cyclin D1 and MMP2." (PMID 36793374, 2023). "Leucine-rich repeat (LRR)-containing 3B (LRRC3B) inhibits proliferation and invasion by targeting β-catenin, cyclin D1, and c-Myc in bladder cancer cells; nevertheless, its expression has been observed to be substantially downregulated in BCa." (PMID 37542643, 2023). "Mechanically, circGLIS3 upregulates the expression of SKP1 by adsorbing miR-1273f and then promotes the expression of cyclin D1, ultimately promoting bladder cancer cell proliferation." (PMID 33656636, 2022). "Previous studies showed that circRNA NR3C1 and circRNA 100284 can regulate the cell cycle of bladder cancer cell by inhibiting or promoting cyclin D1 respectively, thereby affecting the progress of bladder cancer." (PMID 33656636, 2022). "In bladder cancer cells, miR-106a inhibits the expression of cyclin D1 and CDK6 and enhances the p21CIP1/WAF1 pathway, which arrests the cell cycle at the G1 phase." (PMID 36233210, 2022). "Increased SKP1 expression would further promote the expression of cyclin D1, ultimately leading to an abnormally excessive proliferation of bladder cancer cells." (PMID 33656636, 2022). "Mechanically, circGLIS3 upregulates the expression of SKP1 by adsorbing miR-1273f and then promotes cyclin D1 expression, ultimately promoting the proliferation of bladder cancer cells." (PMID 33656636, 2022). "It is already known that KLF5 is a key controller of cell proliferation, as in bladder cancer, where it regulates cyclin D1 or Cyclin E expression." (PMID 35683018, 2022). "Previous studies indicated that CCND1 participated in miR-502-5p-mediated suppression of cell proliferation and migration in bladder cancer." (PMID 34354775, 2021).
bladder cancer (continued). "Consistently, western blot analysis revealed that gemcitabine and MK-8776 treatment for 48 h suppressed the expression of CDK4 and cyclin D1 in bladder cancer cells." (PMID 33986399, 2021). "Among these, NOTCH1, CCND1, CD44, MMP7, TGFR2, and FGFR3 are involved in bladder cancer signaling pathways or are associated with the development of bladder carcinoma." (PMID 33535616, 2021). "In this study, after retrieving and analyzing the Oncomine database, it was found that CCND1 gene was differentially expressed in many tumors, such as bladder cancer and cervical cancer." (PMID 34806539, 2021). "The same effect was obtained on the expression of cyclin D1, whose high levels are related to a poor prognosis and tumour recurrence in many cancers, including bladder cancer." (PMID 33504020, 2021). "It has been revealed that cell proliferation was increased by DXO downregulation and destabilizing cyclin D1 mRNA in bladder cancer." (PMID 34831362, 2021). "Next, we investigated the effect of hAM homogenate on the expression of cyclin D1, which is essential for G1/S phase transition and its overexpression had been recorded in a large proportion of human cancers, including bladder cancer." (PMID 34249888, 2021). "So miR-576-3p played a role as a tumor suppressor in bladder cancer cells by suppressing the CCND1 gene expression. miR-576-3p overexpression in cells with bladder cancer can promote G1-phase arrest." (PMID 32592365, 2020). "Cyclin D1 is an important gene involved in cell cycle progression from G1 to S phase, and overexpression of cyclin D1 has been observed in various cancers, including bladder cancer." (PMID 32605038, 2020). "Cyclin D1 is an important cell cycle mediator, and its expression has been reported to be increased in various cancers, including bladder cancer." (PMID 32605038, 2020). "The TCGA data integrated and analysed by the ONCOMINE database revealed that the expression of CCND1 was markedly reduced in bladder cancer." (PMID 31971654, 2020). "The down-regulation of miR-576-3p raised the CCND1 gene expression and induced the bladder cancer cells multiplication by accelerating the cell cycle progression." (PMID 32592365, 2020). "In the rat model used in this study, carcinogenesis is at an earlier stage than in other rat models of bladder cancer in which increased expression of cyclin D1 has been reported." (PMID 32605038, 2020). "Cyclin D1 functions as a key mitogen, with up to 20% of bladder cancer cases expressing an increase." (PMID 31167517, 2019). "We demonstrated that upregulation NPL4 binds directly to DXO and induces its degradation, whereas DXO regulates bladder cancer cell proliferation via destabilization of cyclin D1 mRNA." (PMID 31164795, 2019). "For example, the overexpression of the cell cycle gene, Cyclin D1 (CCND1), is very common for many cancers, including bladder cancer, and contributes to cancer development." (PMID 29300757, 2018). "Our recent studies show that XIAP upregulates cyclin D1 via its C-terminal RING domain to promote bladder cancer cell growth and enhances colorectal cancer cell motilities through inhibiting the RhoGDIα SUMOlation at the lys-138 site." (PMID 28057023, 2017). "Western blot revealed that Rab27A positively regulated the expression of cyclin E, cyclin D1, suggesting Rab27A induces bladder cancer proliferation through cell cycle proteins." (PMID 29088864, 2017). "Knockdown of p100 significantly enhanced anchorage-independent growth of human bladder cancer cells, also accompanied with activation of Cyclin D1 expression and promotion of the cell cycle progression in UMUC3 and T24 cells." (PMID 27095572, 2016). "Previous reports have shown that the cyclin D1 was constitutively overexpressed in several human tumors including bladder cancer." (PMID 26245871, 2015).
bladder cancer (continued). "We examined the relative gene expression levels in the amiRNAs-transfected bladder cancer cell lines and the mRNA levels of c-Myc, cyclin D1, IGF2, and VEGF were down-regulated by the corresponding amiRNA in the bladder cell lines." (PMID 26541358, 2015). "Suppression of PHLPP2 or FOXO1 by miR-135a, consisted with dysregulation of p21, p27, Cyclin D1 and Ki67, play important roles in bladder cancer progression." (PMID 25888950, 2015). "Cyclin D1 plays a vital role in promoting cell cycle G1/S phases transition, consistently with our findings that the metformin-treated bladder cancer cells were tended to be arrested at G0/G1 phase and the number of S phase cells were greatly decreased." (PMID 26245871, 2015). "Consistently, the expression of p27 was significantly decreased, whereas cyclin D1 was increased in bladder cancer tissues compared with matched ANT." (PMID 26375441, 2015). "In this study, we conducted a systematic review and meta-analysis to estimate the effect of cyclin D1 altered expression on the survival of bladder cancer patients." (PMID 24602161, 2014). "In the present meta-analysis, our results suggest that overexpression of cyclin D1 is a prognostic factor for good PFS in bladder cancer patients." (PMID 24602161, 2014). "The study also suggests potential use of curcumin to target the YAP/TAZ/ KLF5/cyclin D1 axis in bladder cancer treatment." (PMID 25170806, 2014). "For bladder cancer, cyclin D1 also has been reported to play an important role in origin, development, and dissemination of the disease." (PMID 24602161, 2014). "After exclusion of the trials that were out of the scope of our systematic review, 17 studies assessing prognostic value for survival of cyclin D1 status in patients with bladder cancer were considered eligible for inclusion in the evaluation." (PMID 24602161, 2014). "Similar to the findings with the bladder cancer cell lines, CCND1, the chromosome 1q23.3 region, and E2F3-SOX4 were the most commonly amplified, seen in 11 (13%), 8 (10%), and 12 (14%) samples, respectively." (PMID 23593348, 2013). "Previous reports have shown that the cyclin D1 gene (CCND1) is amplified and/or overexpressed in several human tumors including bladder cancer." (PMID 24351837, 2013). "Our data showed intense staining for anti-Cyclin D1 in all tumors, corroborating that the gene CCND1 is frequently amplified in bladder cancer." (PMID 21483670, 2011). "Positive correlation between high heterogeneity, centrosome abnormalities and CCND1 amplification was found in T1G3 bladder carcinomas." (PMID 20540739, 2010). "We also examined the expression of anti-apoptotic genes and cyclin D1 in WH bladder cancer cells when Stat3 pathway was targeted by rAd/dnStat3 or STA-21." (PMID 18939995, 2008). "Overall, 70% of bladder carcinomas showed abnormalities in one or more of the intrinsic proteins of the G1 checkpoint (Rb, p16INK4a and cyclin D1)." (PMID 10376969, 1999). "AKT1, GSK3B, CASP3, TNF, CCND1 are the main targets of COP in the treatment of bladder cancer." (PMID 41287122, 2025). "Taken together, our study provides evidence that targeting C-MYC and Cyclin D1 may be a good strategy for bladder cancer prevention." (PMID 40224178, 2025). "Additionally, in our previous work, we have reported that COP represses the expression level of CCND1 in bladder cancer cells." (PMID 41287122, 2025). "Other miRNAs and transcription factors could also influence the expression of SMAD4, C-MYC, and Cyclin D1, further modulating bladder cancer cell growth and proliferation." (PMID 40224178, 2025). "In this study, through network pharmacology, it was demonstrated that AKT1, GSK3B, CASP3, TNF, and CCND1 may be the crucial targets of COP in bladder cancer treatment." (PMID 41287122, 2025).
bladder cancer (continued). "Similarly, hnRNP K is highly expressed in bladder cancer and can promote bladder cancer proliferation and resist apoptosis by regulating the transcription and translation of mRNAs, such as cyclin D1." (PMID 36831493, 2023). "Further mechanistic experimental studies have indicated that circGLIS3 may competitively bind miR-1273f and promote SKP1 expression, thereby promoting cyclin D1 overexpression, ultimately promoting the proliferation of bladder cancer cells." (PMID 33656636, 2022). "Furthermore, the study has revealed that the overexpression of CCND1 is an independent factor in the metastasis of bladder cancer." (PMID 36430344, 2022). "However, studies have also shown that cyclin D1 is a predictor of good prognosis in patients with urologic cancers, such as renal cell carcinoma and bladder cancer." (PMID 35242498, 2022). "Moreover, CCND1 amplification in primary tumors and metastases predicted cancer-related death independently in bladder cancer." (PMID 35246017, 2022). "We, therefore, tested the inhibitory effect of ANAM‐β on β‐catenin by measuring the expression levels of cyclin D1 and c‐myc in the bladder cancer cell line 5637, which displayed a high expression level of β‐catenin and NF‐κB and a moderate transgene expression efficiency in our previous studies." (PMID 33135339, 2020). "Decreased expression of cyclin D1 was shown in hnRNP‐K suppressing bladder cancer cells." (PMID 30444036, 2019). "Similarly, it has previously been shown that shRNA-mediated silencing of ΔNTP63 expression in 5637 bladder cancer cells resulted in cell cycle arrest, a decreased proliferation rate and Cyclin D1 downregulation." (PMID 29956121, 2018). "Therefore, using Western blot assay and qRT-PCR, we detected the effect of CASC2 on β-catenin expression and a few of the downstream genes of the Wnt/β-catenin signaling pathway, such as, cyclin D1, c-myc and E-cadherin in bladder cancer cells." (PMID 28199978, 2017). "CCND1 gene amplification was previously found to be correlated to histopathological tumor characteristics, cancer-specific survival and response to chemotherapy in bladder cancer." (PMID 28589857, 2017). "Gene amplification is one of the mechanisms underlying the activation of proto-oncogenes such as ERBB2, CCND1, CCNE1, MDM2, and E2F3, which have been suggested as cancer driver genes in bladder cancers, based on their aberrant gene amplification and protein overexpression." (PMID 27902773, 2016). "Similarly, PLCE1 knockdown in bladder cancer reduces proliferating cell nuclear antigen and cyclin D1 in the bladder tumor xenograft, leading to significant inhibition of cell proliferation and cell cycle arrest." (PMID 26657507, 2016). "Furthermore, overexpression of miR-192 significantly induced apoptotic death in bladder cancer cells, increased the levels of p21, p27, and Bax, and decreased the levels of cyclin D1, Bcl-2, and Mcl-125." (PMID 27577949, 2016). "For example, the expression-optimized cutoffs suggest that CCND1 amplifications are overestimated in TCGA head and neck cancer which uses a low threshold (31% vs 18% prevalence) and underestimated in TCGA bladder cancer which uses a high threshold (6% vs 8% prevalence)." (PMID 26787600, 2016).